TBX21 (T-box transcription factor 21)
Description:
Lineage-defining transcription factor which initiates Th1 lineage development from naive Th precursor cells both by activating Th1 genetic programs and by repressing the opposing Th2 and Th17 genetic programs. Activates transcription of a set of genes important for Th1 cell function, including those encoding IFN-gamma and the chemokine receptor CXCR3. Induces permissive chromatin accessibility and CpG methylation in IFNG. Activates IFNG and CXCR3 genes in part by recruiting chromatin remodeling complexes including KDM6B, a SMARCA4-containing SWI/SNF-complex, and an H3K4me2-methyltransferase complex to their promoters and all of these complexes serve to establish a more permissive chromatin state conducive with transcriptional activation (By similarity). Can activate Th1 genes also via recruitment of Mediator complex and P-TEFb (composed of CDK9 and CCNT1/cyclin-T1) in the form of the super elongation complex (SEC) to super-enhancers and associated genes in activated Th1 cells. Inhibits the Th17 cell lineage commitment by blocking RUNX1-mediated transactivation of Th17 cell-specific transcriptinal regulator RORC. Inhibits the Th2 cell lineage commitment by suppressing the production of Th2 cytokines, such as IL-4, IL-5, and IL-13, via repression of transcriptional regulators GATA3 and NFATC2. Protects Th1 cells from amplifying aberrant type-I IFN response in an IFN-gamma abundant microenvironment by acting as a repressor of type-I IFN transcription factors and type-I IFN-stimulated genes. Acts as a regulator of antiviral B-cell responses; controls chronic viral infection by promoting the antiviral antibody IgG2a isotype switching and via regulation of a broad antiviral gene expression program (By similarity). Required for the correct development of natural killer (NK) and mucosal-associated invariant T (MAIT) cells.
Synonyms: TBET; TBLYM; T-bet; IMD88; T-PET
Tractability: PROTAC: UniProt records ubiquitination sites on it; ubiquitination databases record sites on it; its protein half-life has been measured.
Gene: Protein-coding gene on chromosome 17 (47,733,236 to 47,746,126, forward strand). Ensembl gene ENSG00000073861.
Subcellular location: Nucleus
Pathways (Reactome):
Developmental Biology: Differentiation of naive CD4+ T cells to T helper 1 cells (Th1 cells); Differentiation of naive CD4+ T cells to T helper 2 cells (Th2 cells)
Gene Ontology:
Molecular function: DNA-binding transcription repressor activity, RNA polymerase II-specific; protein binding; sequence-specific DNA binding; sequence-specific double-stranded DNA binding; transcription cis-regulatory region binding; DNA-binding transcription factor activity, RNA polymerase II-specific; RNA polymerase II cis-regulatory region sequence-specific DNA binding; DNA binding; DNA-binding transcription activator activity, RNA polymerase II-specific; DNA-binding transcription factor activity
Biological process: lymphocyte migration; negative regulation of transcription by RNA polymerase II; positive regulation of DNA-templated transcription; response to virus; cell fate specification; negative regulation of DNA-templated transcription; negative regulation of interleukin-2 production; negative regulation of T-helper 17 cell differentiation; negative regulation of T-helper 17 cell lineage commitment; negative regulation of T-helper 2 cell cytokine production; positive regulation of T-helper 1 cell cytokine production; positive regulation of transcription by RNA polymerase II; proteasome-mediated ubiquitin-dependent protein catabolic process; regulation of T cell differentiation; regulation of transcription by RNA polymerase II; T-helper 1 cell lineage commitment; leukocyte migration involved in inflammatory response; regulation of DNA-templated transcription; response to dexamethasone
Cellular component: nucleus; chromatin; cytoplasm; neuronal cell body
Genetic constraint (gnomAD): Loss-of-function variants: 11 observed, 47.79 expected, observed/expected ratio (o/e) 0.23, 90% interval 0.14 to 0.38. The upper end of that interval is the gene's LOEUF score, 0.38, which puts it in group 1 of 6, group 1 being the genes least tolerant of losing a copy. Missense variants: 625 observed, 704.93 expected, observed/expected ratio (o/e) 0.89, 90% interval 0.83 to 0.95. Synonymous variants: 300 observed, 291.6 expected, observed/expected ratio (o/e) 1.03, 90% interval 0.94 to 1.13.
Homologues: Orthologues: chimpanzee TBX21 (100% identical), pig TBX21 (94% identical), dog TBX21 (93% identical), macaque TBX21 (92% identical), mouse Tbx21 (86% identical), rabbit TBX21 (86% identical), rat Tbx21 (86% identical), guinea pig TBX21 (66% identical), zebrafish tbx21 (47% identical), tropical clawed frog tbx21 (39% identical), zebrafish tbxta (22% identical), Drosophila melanogaster Doc2 (21% identical), and 13 more. Paralogues in human: EOMES (43% identical), TBR1 (42% identical), TBX4 (24% identical), MGA (23% identical), TBX5 (23% identical), TBX2 (23% identical), TBX1 (22% identical), TBXT (22% identical), TBX15 (21% identical), TBX19 (21% identical), TBX18 (21% identical), TBX3 (21% identical), and 4 more.
Diseases named in the same sentence as TBX21 in open-access papers:
TBX21 is named in the same sentence as 155 diseases in open-access papers, as found by Europe PMC text mining. Sharing a sentence is not in itself a finding about the gene and the disease. The quoted sentences say what the papers report.
colitis (30 papers, 2012 to 2025). Inflammation of the colon. "Specifically, TBX21 deletion in dendritic cells promotes colitis-associated colorectal carcinogenesis 13, and TBX21 has been implicated in lung carcinogenesis via the TBX21/IL-4 signaling pathway." (PMID 39744435, 2025). "T-bet deficiency within the innate immune compartment results in spontaneous colitis triggered by Helicobacter typhlonius, which drives excess TNF-α production and promotes colitis in Tbx21−/−Rag2−/− ulcerative colitis (TRUC) mice." (PMID 35163778, 2022). "We have demonstrated that Tbx21-/- mice on a BALB/c Rag2-/- background are more susceptible to H. thyphlonius-driven colitis in comparison to conventional BALB/c background Rag2-/- mice pointing to a protective role of T-bet." (PMID 34795671, 2021). "Similar to Tbx21-/- mice, Tbx21Δ mice showed a milder course of colitis with less weight loss and a lower diarrhoea score than Tbx21fl mice while mice receiving fresh water did not develop disease." (PMID 34795671, 2021). "Overexpression of T-bet in CD4+ T cells exacerbated experimental colitis, whereas Tbx21-deficient CD4+ T cells were unable to modulate the development of colitis." (PMID 32369982, 2020). "To test which effector cytokines were required for colitis induced by T-bet-deficient T cells, we transferred cohorts of Rag1−/− recipients with WT or Tbx21−/− T cells and administered neutralizing antibodies to IL-17A or IL-22." (PMID 27193261, 2016). "Hence, Tbx21-/- mice appeared to be resilient to spontaneous colitis driven by the pathogenic microbes used." (PMID 33603753, 2020). "Tbx21-deficient mice develop more severe colitis than control animals after treatment with DSS." (PMID 29910812, 2018). "To test this hypothesis, we compared the phenotypes of Tbx21+/+ and Tbx21−/− intestinal ILCs in H. typhlonius-associated colitis in TRnUC and Rag2−/− mice." (PMID 23063332, 2012). "We have previously shown that spontaneous colitis in Tbx21-/- x Rag2-/- ulcerative colitis (TRUC) mice is partially driven by IL-17A-producing CD90+ ILC." (PMID 37114052, 2023). "We did also observe milder DSS-induced colitis in mice with a germline deletion of Tbx21, and this was observed in both Rag-sufficient and -deficient mice." (PMID 34795671, 2021). "Experiments in Tbx21 (T-bet) and Ifng (IFN-γ) deficient mice have confirmed that IFN-γ is a major mediator involved in OVA-induced colitis." (PMID 30949176, 2019). "The expression of Th1 cell marker tbx21 was higher in WT fish compared to il10e46/e46 mutants (P = 0.023) but this is unlikely a sign towards colitis in il10e46/e46 mutants." (PMID 29985419, 2018). "Tbx21-deficient CD4 T cells, isolated from BALB/c mice, were unable to induce colitis in a SCID adoptive transfer model of IBD." (PMID 29910812, 2018). "To elucidate the impact of RORγt and T-bet expression on the colitogenic potential of T cells, we transferred Rag1−/− mice with CD4+ T cells from C57BL/6 WT, Tbx21−/− or Rorc−/− donors and assessed the development of colitis." (PMID 27193261, 2016). "Tbx21-/-Rag2-/- ulcerative colitis (TRUC) mice spontaneously develop severe colitis with striking similarities to some aspects of human UC." (PMID 25917784, 2015). "Predicted upstream regulators of ILCs in CPI-C included Tbx21, encoding the transcription factor T-bet, and genes encoding the cytokines Il2, Il18 and Il21, suggesting that ILC1 may contribute to colitis in this model." (PMID 39496592, 2024). "BALB/c and BALB/c-background Tbx21-/- mice were more resistant to DSS-induced colitis as these mice did not experience weight loss in this model." (PMID 34795671, 2021). "In contrast to studies suggesting that ILC1 promote colitis, we have reported previously that T-bet expression can also protect from colitis, as Rag2-/- mice with germline deletion of Tbx21 can develop spontaneous colitis if Helicobacter thyphlonius is present in the gut." (PMID 34795671, 2021).
colitis (continued). "Tbx21-deficient mice lack ILC1 and NKp46+ ILC3, hence, we addressed the functionality of NKp46- ILC3, which may also have a pathogenic role in colitis." (PMID 33603753, 2020). "In addition, we observed down-regulation in the expression of the transcription factors TBX21/T-bet in the colon cells of rBmaCys-treated colitis mice." (PMID 31683524, 2019). "Despite the greater ILC3 cellularity, Tbx21-deficient mice did not develop spontaneous colitis." (PMID 33603753, 2020). "We have reported that immunocompetent Tbx21-deficient mice do not develop spontaneous colitis." (PMID 33603753, 2020). "Encouragingly, Tbx21 deficient mice on a BALB/c background do not develop spontaneous colitis." (PMID 33603753, 2020). "Consistently, the transcript levels of Ifn‐γ, Tbx21 and Tnf‐α were elevated while Foxp3 and Il10 levels were decreased of TNBS‐induced Atg7ΔCD4 colitis mice relative to littermate controls born with Atg7fl/fl." (PMID 40887825, 2025). "Similar to the reported effects of MSCs in chemically-induced colitis, BM-MSC treatments in Winnie mice downregulated the expression of Il6, Ifng, Il1b, Il1a, Tnf, Cxcl2, Tbx21 and Itgam, which were upregulated in Winnie mice and IBD patients." (PMID 38503815, 2024). "ILCs were isolated from colons of Tbx21-/- × Rag2-/- mice (TRUC), which develop colitis; patients with inflammatory bowel disease (IBD); and patients without colon inflammation (controls)." (PMID 25917784, 2015). "In contrast, Rag-sufficient mice with a germline depletion of Tbx21 have a greater cellularity of intestinal NKp46-negative ILC3 while demonstrating no sign of spontaneous colitis." (PMID 34795671, 2021). "Transfer of Tbx21–/– naïve CD4+ T cells into Rag2–/– mice gives rise to a higher proportion of IL‐17A‐producing CD4+ T cells and more severe colitis compared to mice receiving WT naïve CD4+ T cells, suggesting that T‐bet restrains pathology in IL‐17‐driven colitis." (PMID 35092032, 2022). "Importantly, the excision of Tbx21 in IL-17–producing cells had no impact on H. hepaticus-induced intestinal pathology, indicating that, in this model, Th17 cell transition to IFN-γ–producing Th1-like cells is not absolutely required for colitis development." (PMID 27183623, 2016). "We show that the IL-17ACre– or Rag1Cre-mediated removal of Tbx21 does not impact on the generation of IL-17/IFN-γ double producers, but markedly blocks the generation of Th17 cell–derived Th1-like cells during H. hepaticus-induced colitis without reducing immunopathology." (PMID 27183623, 2016).
asthma (22 papers, 2006 to 2025). "For instance, rs4794067 of TBX21 is related to a higher risk of severity of asthma, risk of lupus erythematosus, and type 1 autoimmune hepatitis." (PMID 37950255, 2023). "The T-box transcription factor Tbx21 (T-bet) maintains Th1 cell development and loss of T-bet is associated with a shift towards Th2 type allergic airway inflammation that characterizes asthma." (PMID 24499286, 2014). "TBX21 polymorphisms were associated with airway hyperresponsiveness in asthma and increased risk for childhood asthma." (PMID 22303482, 2012). "For TBX21 polymorphisms, several studies have shown an association with the development of asthma indicating the relevance of TH1 TFs in TH2-associated allergic diseases." (PMID 22303482, 2012). "Additionally, a study of gene variants in T-cell-specific TBX21, a factor that induces TH1 differentiation and blocks TH2 commitment together with HLX1, suggests that TBX21 polymorphisms contribute to asthma, possibly through altered TBX21 promoter activity." (PMID 36313877, 2022). "This study investigated the influence of TBX21 and HLX1 single nucleotide polymorphisms (SNPs), which have previously been shown to be associated with asthma, on TH1/TH2 lineage cytokines at birth." (PMID 22303482, 2012). "Like TBX21, polymorphisms in HLX1 have also been significantly associated with the development of childhood asthma." (PMID 22303482, 2012). "While TBX21 is not known to be involved in lung morphogenesis, mice studies showed that Tbx21 deficiency induces a phenotype reminiscent of human asthma." (PMID 33478486, 2021). "Since BHR and asthma control level are related to the quality of life in asthma patients and prognosis of asthma, genetic variation in TBX21 may be important for asthma phenotypes." (PMID 30647901, 2019). "Both studies investigating TBX21 H33Q and ICS response showed significant association measured by two different outcomes: improvement in BHR in one childhood study of 4 years duration, and asthma control status in a 5–12 weeks adult study." (PMID 30647901, 2019). "The further follow-up of our cohort will help to elucidate which of these children will also develop atopic diseases and/or asthma and whether the TBX21 and HLX genotypes have an impact on their later immune development." (PMID 22303482, 2012). "We aimed to study two TBX21 (rs17250932, rs11079788) and three HLX1 (rs2738751, rs3806325, rs12141189) polymorphisms, which have previously been associated with risk or protection from childhood asthma." (PMID 22303482, 2012). "Less clear is the mechanism behind childhood asthma loci such as 6p25.3 near IRF4 and 17q21.32 near TBX21, which we associate here with CRSwNP but not asthma." (PMID 41213931, 2025). "Several studies on multiple sclerosis and asthma found that MALAT1 and NEAT1 regulate the RUNX3–GATA3/TBX21 axis, key transcription factors (TFs) in T cell differentiation, by regulating the expression levels of the related miRs, thereby influencing the direction of the Th1/Th2 bias." (PMID 38006062, 2023). "However, we were not able show any association between TBX21 H33Q and FEV1 4 h after single-high-dose ICS in children with moderate-severe asthma exacerbation." (PMID 30647901, 2019).
breast carcinoma (13 papers, 2016 to 2025). "In order to assess the role of Th1 cells in canine mammary tumors, we investigated the expression of TBX21, a gene that encodes the T-bet protein, a major transcription factor that controls the differentiation of naïve T cells into the Th1 lineage." (PMID 32225066, 2020). "Our results indicate that in malignant canine mammary tumors, similar to human breast cancers, TBX21 expression might be associated with a more favorable prognosis related to a low metastatic potential for the cancer." (PMID 32225066, 2020). "Gene expression analysis revealed IFNG, CXCR5, CD40LG, TBX21 and IL2RG to be associated with the CSC phenotype and also displayed prognostic value for patients with breast cancer." (PMID 38831317, 2024). "Gene expression analysis from in vitro mammosphere formation revealed IFNG, CXCR5, CD40LG, TBX21, and IL2RG to be associated with the CSC phenotype and also displayed prognostic value for patients with breast cancer." (PMID 39001456, 2024). "It was confirmed in another study that high expression of TBX21 is related to poor prognosis of patients with breast cancer and lung adenocarcinoma." (PMID 35163468, 2022). "The first one shows that the transcriptome signals obtained from TBX21 are highly correlated with downstream signal of the Up gene CD48 (r = 0.86) in the breast cancer case (n = 1093)." (PMID 31227749, 2019). "Generally, our study identified three mRNAs (TBX21, TGIF2, and CYCS) that were significantly altered between high‐ and low‐risk patients with breast cancer." (PMID 30632703, 2019). "The second graph shows that the gene expression levels of TBX21 and its BioTarget identified Down gene TTC26 are negatively correlated (r = −0.26) in the breast cancer case." (PMID 31227749, 2019). "Bioinformatic analysis in breast cancer has shown that high expression of IL-12/STAT4 axis molecules, such as the IL-12 receptor genes (IL-12RB1 and IL-12RB2), STAT4, IFNγ, and TBX21, significantly increases the survival rates of patients with breast cancer, especially the more aggressive subtypes." (PMID 33076315, 2020). "The physiological subcellular localization of TBX21 is regulated by PD1 in T-cells and aberrant enhancement of nuclear import from the cytoplasm has been reported for TBX2 in breast cancer cells, indicating that this type of regulation may play a role for the related TBX3 as well." (PMID 34807923, 2021).
COVID-19 (12 papers, 2021 to 2024). A disease caused by infection with severe acute respiratory syndrome coronavirus 2. "For instance, we observed significantly stronger enrichment of TBX21 (adjusted P = 1 × 10−224), RUNX3 (adjusted P = 1 × 10−199), TCF7L2 (adjusted P = 1 × 10−167) and ZEB1 (adjusted P = 1 × 10−118) motifs in severe COVID-19 risk variant-depleted cells." (PMID 35668323, 2022). "In addition, we noticed that the memory population A1 contained high amounts of atypical memory B cells (aTMs) with low T-bet (TBX21) expression in line with previous flow cytometry data from COVID-19 and malaria patients." (PMID 34723157, 2021). "Indeed, both scATAC-seq and scRNA-seq KEGG analyses revealed the TNF signaling pathway to be involved in COVID-19; the scATAC-seq data showing lower TBX21 locus accessibility were consistent with the scRNA-seq data, showing decrease in Th1 cells of SCPs compared to the MCPs and HCs." (PMID 33717140, 2021). "(D) Log2 percent AREG+ ILCs in blood of controls or people hospitalized with COVID-19 after stimulation with PMA and ionomycin and gated as Lin-TBX21-." (PMID 35275061, 2022). "Severe COVID-19 patients that develop lung injury showed expanded KLRG1+ Tregs that express Cxcr3, Il10, Il12b1, Ilrb1, Tbx21, Gata3 gene signatures similar to what was found in this study." (PMID 35634302, 2022). "Moreover, TBX21 and FOXP3, the main transcriptional factors for TH1 cells and TREG cells, respectively, have been found to be overexpressed in patients with poor outcomes in COVID-19." (PMID 38298642, 2024).